GPNMB (glycoprotein nmb)
Diseases named in the same sentence as GPNMB in open-access papers (continued):
Sharing a sentence is not in itself a finding about the gene and the disease.
glaucoma (2 papers, 2008 to 2015). Increased pressure in the eyeball due to obstruction of the outflow of aqueous humor. "The pigmentary form of glaucoma in DBA/2J mice depends upon mutations in the two melanosomal proteins TYRP1 (tyrosinase-related protein 1) and GPNMB (glycoprotein nmb)." (PMID 25755083, 2015). "In the present study, GPNMB was sharply upregulated in optic nerve head astrocytes of Caucasian American donors with glaucoma." (PMID 18822132, 2008). "The DBA/2J has immune system defects and immune roles for GPNMB in glaucoma must be investigated further, as GPNMB can function as a feedback regulator of macrophage activation." (PMID 18822132, 2008). "Two genes, NEFH and GPNMB, exhibited higher fold increases in samples with moderate to advanced glaucoma." (PMID 18822132, 2008). "Two distinct eye diseases produce glaucoma in the DBA/2J strain – iris pigment dispersion syndrome, which was mapped to a null mutation in GPNMB, and iris stromal atrophy, which was mapped to a mutation in TYRP1." (PMID 18822132, 2008). "Differential expression of motility genes, including capping protein G (CAPG) and transforming growth factor beta-induced (TGFBI), was consistent with the reactive, migratory astrocyte phenotype characteristic of glaucoma, as were ECM remodeling genes, such as GPNMB and TIMP1." (PMID 18822132, 2008). "In sample 566, GPNMB variation may be due to infiltration of the ONH with microglia or macrophages, as has been previously reported in advanced glaucoma in humans." (PMID 18822132, 2008).
Hypertension (2 papers, 2023 to 2024). The presence of chronic increased pressure in the systemic arterial system. "Additionally, we found that hypertension was associated with cg17274742 hypermethylation, which could decrease GPNMB expression and potentially reduce PD risk." (PMID 39091454, 2024). "Furthermore, our findings indicate that hypertension is associated with hypermethylation of cg17274742, which could reduce the expression of GPNMB and therefore possibly lower the risk of PD." (PMID 37744396, 2023).
ischemia (2 papers, 2018 to 2019). A hypoperfusion of the BLOOD through an organ or tissue caused by a PATHOLOGIC CONSTRICTION or obstruction of its BLOOD VESSELS, or an absence of BLOOD CIRCULATION. "GPNMB has demonstrated a neuroprotective role in animal models of ALS and ischemia." (PMID 29519253, 2018).
liver cancer (2 papers, 2023 to 2025). An epithelial or non-epithelial malignant neoplasm that arises from the liver. "Another liver cancer study show that GPNMB expressed by tumor endothelial cells plays a significant role." (PMID 41180454, 2025). "Therefore, GPNMB is crucial in the immune escape of liver cancer and is a potential therapeutic target." (PMID 41180454, 2025).
liver disease (2 papers, 2025 to 2026). "Conversely, the presence of markedly elevated gpNMB concentrations in individual treated patients—especially those with liver disease and monoclonal gammopathy—deserves further exploration." (PMID 41152894, 2025). "Patients with overt liver disease (n = 14) in association with GD also had higher gpNMB concentrations than those without liver disease (p<0.05)." (PMID 41152894, 2025).
lymph node metastasis (2 papers, 2022). "In the cases with lymph node metastasis, the GPNMB-positive cells were more concentrated in the lymph nodes than in the primary tumor." (PMID 36061142, 2022). "We also compared the intensity of primary and metastatic lymph nodes by immunostaining them with GPNMB in a case of actual lymph node metastasis and found that GPNMB-positive cells were more concentrated in the metastatic lymph nodes than in the primary tumor." (PMID 36061142, 2022). "GPNMB was expressed higher in the AJCC III stage, lymph node metastasis, and moderately poorly differentiated patients." (PMID 36090016, 2022). "GPNMB expression was higher in the lymph node metastasis group than in the nonmetastasis group (P <0.001)." (PMID 36090016, 2022).
metabolic syndrome (2 papers, 2018). A cluster of metabolic risk factors for CARDIOVASCULAR DISEASES and TYPE 2 DIABETES MELLITUS. "GPNMB is also increased in several acquired diseases, such as the metabolic syndrome and neurodegeneration." (PMID 30586924, 2018). "In addition, we assessed GPNMB plasma levels among 389 HF cases and controls from the METabolic Syndrome In Men (METSIM) study." (PMID 30201759, 2018).
metastatic tumor (2 papers, 2025). "We identify GPNMB as a marker of quiescence, that is expressed in both primary and metastatic tumors." (PMID 40528051, 2025). "This analysis revealed that SREBF1 and GPNMB were downregulated in metastatic tumor fibroblasts compared to their primary tumor counterparts, and HIF1A was downregulated in metastatic tumor cells compared to primary tumor cells." (PMID 40095604, 2025).
myocardial infarction (2 papers, 2018 to 2023). Gross necrosis of the myocardium, as a result of interruption of the blood supply to the area, as in coronary thrombosis. "In the myocardial infarction model, GPNMB mRNA transcript was up-regulated 17-fold in the peri-infarct (PI) area in the rat and 300-fold in the mouse at 24 hr and 7 days after myocardial infarction, respectively." (PMID 30201759, 2018).
Nasu-Hakola disease (2 papers, 2021 to 2024). "Alteration of GPNMB protein expression is closely linked with Nasu-Hakola disease (NHD), which is a rare autosomal recessive disorder characterized by progressive presenile dementia." (PMID 34827437, 2021).
pancreatic cancer (2 papers, 2023 to 2025). "Given the connection between glycolysis and stemness in cancer cells and previous findings obtained from pancreatic cancer and fibrosarcoma, showing that TAM-derived GPNMB can promote cancer cell stemness, we further observed that GPNMB is a key factor driving GSC self-renewal." (PMID 40626360, 2025). "Similarly, GPNMB+ MDSCs isolated from CAC and pancreatic cancer patients exhibited significant suppressive effect on T cell function." (PMID 38140790, 2023).
Sepsis (2 papers, 2025 to 2026). Sepsis is defined as life-threatening organ dysfunction caused by a dysregulated host response to infection. "In sepsis, Microglia 1 exhibited strong upregulation of pro-inflammatory genes (e.g., GPNMB, CXCR4, HLA-DRB5) and downregulation of BBB-supportive genes (e.g., SPARCL1, MAP1B), indicating a highly reactive phenotype." (PMID 41030458, 2025).
silicosis (2 papers, 2023). Silicosis is a respiratory disease caused by breathing in (inhaling) silica dust. "GPNMB participates in the epithelial-mesenchymal transition in distant lung epithelial cells by releasing extracellular vesicles to accelerate silicosis." (PMID 37468937, 2023). "Immunofluorescence staining showed that GPNMB produced by macrophages could reliably bind to the ECM, thus indicating that the GPNMB in the fibrotic ECM of silicosis mice was derived from macrophages." (PMID 36732560, 2023).
Stroke (2 papers, 2017 to 2025). Sudden impairment of blood flow to a part of the brain due to occlusion or rupture of an artery to the brain. "Thus, from the therapeutic perspective, elucidation of the role of GPNMB in stress responses may lead to better treatments of several disorders, including stroke, neurodegenerative and muscle diseases, and several cancers." (PMID 28939899, 2017).
acute kidney injury (1 paper, 2017). Sudden and sustained deterioration of the kidney function characterized by decreased glomerular filtration rate, increased serum creatinine or oliguria. "In other pathological conditions, such as in acute kidney injury, GPNMB functions as a negative regulator of inflammation by promoting IL-10 and TGF-β secretion." (PMID 29123519, 2017).
acute liver failure (1 paper, 2023). Rapid deterioration of liver function causing encephalopathy and coagulopathy. "In this retrospective study, we assessed whether GPNMB levels in the serum and injured liver correlate with liver injury severity and prognosis in patients with ALI or acute liver failure (ALF)." (PMID 37941897, 2023).
Anxiety (1 paper, 2026). Intense feelings of nervousness, tension, or panic often arise in response to interpersonal stresses. "Multi-omic integration identified RAB27B as a driver of the anxiety-related pathway, implicating synaptic vesicle trafficking and neuroimmune regulation, while GPNMB and KLHL7 supported anxiety-independent pathways involving musculoskeletal remodeling and peripheral inflammation." (PMID 41796324, 2026).
autoimmune hepatitis (1 paper, 2023). Hepatitis caused by autoantibodies. "However, there were a few GPNMB-positive macrophages in patients with autoimmune hepatitis treated with steroids." (PMID 37941897, 2023).
benign breast disease (1 paper, 2015). "We also measured GPNMB for 16 patients with benign breast disease, including patients with fibroadenoma and mastopathy, and cancer-free patients, whose GPNMB level was 8.029 ng/mL which was not statistically different from that of BC, CC, and GC patients." (PMID 26077887, 2015).
bone metastasis (1 paper, 2024). Transfer of a neoplasm from its primary site to bones. "Higher GPNMB concentration groups positively correlated with liver metastasis (P=0.040), while it is similar regarding to different T stage (P=0.230), N stage (P=0.134), M stage (P=0.595), brain metastasis (P=0.493) and bone metastasis (P=0.230)." (PMID 38706915, 2024). "Moreover, we found that the plasma GPNMB concentration in liver metastasis were particularly higher than bone metastasis (P = 0.031), brain metastasis (P = 0.035) and non-organ metastasis (P = 0.005)." (PMID 38706915, 2024).
brain hemorrhage (1 paper, 2024). "They showed that GPNMB+ monocytes contribute to SMC depletion and are associated with bAVM rupture and brain hemorrhage." (PMID 38201296, 2024).
cerebral infarct (1 paper, 2025). "A recent animal experiment showed that PCSK9 inhibitor evolocumab improved neurobehavioral functions and reduced cerebral infarct volumes, which may be mediated by attenuating neuroinflammation through activation of the GPNMB/CD44 pathway." (PMID 41368357, 2025).
cervical cancer (1 paper, 2018). A primary or metastatic malignant neoplasm involving the cervix. "In this study, we found that Wnt/β-catenin pathway was activated, but was attenuated by GPNMB siRNA in cervical cancer cells and the activated Wnt/β-catenin signaling was associated with GPNMB-mediated cervical cancer tumorigenesis in vitro." (PMID 30484490, 2018). "To further clarify the underlying role of GPNMB dysfunction in tumorigenesis of cervical cancer, we silenced GPNMB gene by specific siRNA in SiHa and HeLa cells." (PMID 30484490, 2018). "We investigated whether Wnt/β-catenin pathway was associated with GPNMB-mediated cervical cancer tumorigenesis in vitro." (PMID 30484490, 2018). "However, the underlying role and mechanism of GPNMB in tumorigenesis of human cervical cancer remain incompletely known." (PMID 30484490, 2018). "In the present study, we found that GPNMB expression was significantly increased in cervical cancer." (PMID 30484490, 2018). "In the present study, we aimed to investigate the role of GPNMB in cervical cancer by determining the expression of GPNMB in cervical cancer and cells." (PMID 30484490, 2018). "A similar pattern was observed in GPNMB expression in cultured cervical cancer cells and normal cervical epithelial cells." (PMID 30484490, 2018). "We herein determined that expression and activity of MMP-2 and MMP-9 were aberrantly increased, but were significantly decreased by GPNMB siRNA in cervical cancer cells in vitro." (PMID 30484490, 2018). "Results indicated that GPNMB expression was kept at a low level in normal cervical epithelial cells, but was aberrantly increased in all cervical cancer cells." (PMID 30484490, 2018). "Results indicated that GPNMB expression was kept at low levels in normal cervical epithelial cells, implying the probable involvement of GPNMB in the progression of cervical cancer." (PMID 30484490, 2018). "Based on the GEO database, GPNMB expression was significantly up-regulated in cervical cancer compared with normal cervix epithelium." (PMID 30484490, 2018). "In the present study, we determined the role of glycoprotein nonmetastatic melanoma protein B (GPNMB) in tumorigenesis of cervical cancer." (PMID 30484490, 2018). "According to the GEO database, we found that GPNMB expression was significantly higher in cervical cancer than in normal cervix epithelium." (PMID 30484490, 2018). "Taken together, our results indicated that dysregulation of GPNMB expression played a positive role in the motility of cancer cells, contributing to the tumorigenesis of cervical cancer." (PMID 30484490, 2018). "We further measured the expression levels of GPNMB in human cervical cancer HeLa, ME-180, and SiHa cells." (PMID 30484490, 2018). "In conclusion, we demonstrated that GPNMB contributed to the tumorigenesis of cervical cancer, at least in part, by regulating MMP-2/MMP-9 activity in tumor cells via activation of canonical Wnt/β-catenin signaling." (PMID 30484490, 2018). "Herein, we also determined that GPNMB can accelerate the motility of cancer cells in vitro, which might contribute to tumorigenesis of cervical cancer." (PMID 30484490, 2018). "It would be very interesting to clarify whether there are possible associations among GPNMB, MMP-2/MMP-9, and HPV oncogenes, and whether GPNMB plays a role in HPV-negative cervical cancer cells in future study (26, –28)." (PMID 30484490, 2018). "In conclusion, we demonstrated that GPNMB expression was aberrantly regulated in cervical cancer." (PMID 30484490, 2018). "Furthermore, we found that GPNMB accelerated the tumorigenesis of cervical cancer in vitro by regulating MMP-2/MMP-9 activity via the Wnt/β-catenin pathway." (PMID 30484490, 2018).
Cholecystitis (1 paper, 2015). The presence of inflammatory changes in the gallbladder. "In addition, patients with benign diseases, such as cholecystitis, or (seemingly) healthy volunteers showed high levels of GPNMB without malignancy." (PMID 26077887, 2015).
chronic lung disease (1 paper, 2024). According to the definitions of the American and British Thoracic Societies, including pulmonary functional tests, X-rays, and CT scans for items such as fibrosis, bronchiectasis, bullae, emphysema, nodular or lymphomatous abnormalities. "This relatively prolonged time course also implies a likelihood of detecting a GPNMB+ alveolar macrophage signature in chronic lung disease even long after the time of a previous infection." (PMID 39052353, 2024).
colitis (1 paper, 2021). Inflammation of the colon. "Interestingly, D2 mice, which is a mice strain known to have a premature stop codon mutation in the GPNMB gene, had a more severe condition of colitis, accompanied by increased levels of pro-inflammatory cytokines." (PMID 34054862, 2021). "In colitis, a chronic inflammatory disease in the intestine, infiltrating macrophages in the injured mucosa express GPNMB, and GPNMB expression increases according to the severity of the illness." (PMID 34054862, 2021).
COVID-19 (1 paper, 2022). A disease caused by infection with severe acute respiratory syndrome coronavirus 2. "Based on our finding, allele G plays a positive role against COVID-19 by reducing IL-6, which is consistent with the function of GPNMB in that it weakens the immune response against cancer cells and infections, contributing to cancer development or chronic infections." (PMID 35368020, 2022).
emphysema (1 paper, 2020). "Notably, an ectodomain of GPNMB may be cleaved out by MMP-type protease ADAM10, known to promote emphysema of the lungs, and shed into circulation as a soluble, biologically active molecule with angiogenic properties." (PMID 32478378, 2020).
End Stage Liver Disease (1 paper, 2023). Final stage of a liver disease when the liver failure is irreversible and LIVER TRANSPLANTATION is needed. "The peak GPNMB level correlated with prothrombin activity, prothrombin time-international normalized ratio, Model for End-stage Liver Disease score, and serum hepatocyte growth factor level." (PMID 37941897, 2023).
hemorrhagic stroke (1 paper, 2023). A stroke caused by a bleed on the brain. "Thirdly, GPNMB has a variety of physiological and pathological effectiveness on diseases in central nervous system including hemorrhagic stroke, anti-neuroinflammation is one of the perspectives." (PMID 37919457, 2023).
kidney cancer (1 paper, 2022). Primary or metastatic malignant neoplasm involving the kidney. "In kidney cancer, SLC7A11-positive macrophages were mainly detected in GPNMB positive or FN1 positive macrophage sub-clusters." (PMID 36470862, 2022).
lepromatous leprosy (1 paper, 2025). A chronic communicable infection which is a principal or polar form of leprosy. "We highlight the glycoprotein nonmetastatic melanoma protein B (GPNMB), which is highly expressed in macrophages from lepromatous leprosy (L-Lep) patients and interferes with xenophagy during bacterial infection." (PMID 40038549, 2025).
liposarcoma (1 paper, 2017). A usually painless malignant tumor that arises from adipose tissue. "Similar changes of GPNMB and G0S2 expression were present in a human liposarcoma database." (PMID 28459858, 2017).
lymphangioleiomyomatosis (1 paper, 2025). A multifocal neoplasm with perivascular epithelioid cell differentiation affecting almost exclusively females of child-bearing age. "Notably, GPNMB shows consistent overexpression in rare lymphangioleiomyomatosis lesions, expanding its diagnostic utility." (PMID 41180454, 2025). "Small Molecule Inhibitors: mTOR inhibitors like rapamycin indirectly suppress GPNMB in lymphangioleiomyomatosis (LAM), reducing tumor growth by 60% in murine models." (PMID 41180454, 2025).
malignant brain tumors (1 paper, 2025). "Recent studies on malignant brain tumors have found that GPNMB-high macrophage clusters, such as MG3-GPNMB and MDM3-GPNMB belong to lipid-laden macrophages." (PMID 41180454, 2025).
meningioma (1 paper, 2015). A generally slow growing tumor attached to the dura mater. "However, when looking at meningioma, a benign tumor of the meninges, the expression of GPNMB was higher in the CD11b- cell fraction, compared to the CD11b+ cell fraction." (PMID 25658639, 2015).
monoclonal gammopathy (1 paper, 2025). A condition characterized by the abnormal presence of monoclonal immunoglobulins in the blood or urine. "In a previous study, gpNMB in the cohort of monoclonal gammopathy of undetermined significance (MGUS) in the general population exhibited the greatest expression compared with the control group." (PMID 41152894, 2025).
motor neuron diseases (1 paper, 2018). "As GPNMB has been previously implicated in motor neuron diseases, spinal cord samples from aged 5XFAD mice were analyzed where Aβ pathology has been previously demonstrated." (PMID 30340518, 2018).
multiple myeloma (1 paper, 2025). "Even though gpNMB is considered to be a potent angiogenic factor in gammopathies and multiple myeloma, the extent to which if any, it contributes to the pathogenesis of the cancer and its progression is unknown." (PMID 41152894, 2025).
Oral leukoplakia (1 paper, 2026). A thickened white patch on the oral mucosa that cannot be rubbed off. "Fine-mapping revealed 14 coding variants, such as a missense variant in USP31 for caries and in MANBA for oral leukoplakia, and a stop-gained variant in GPNMB for temporomandibular disorders." (PMID 42310951, 2026).
osteopetrosis (1 paper, 2023). Osteopetrosis, also known as marble bone disease, is a descriptive term that refers to a group of rare, heritable disorders of the skeleton characterized by increased bone density on radiographs. "Glycoprotein non-metastatic melanoma protein B (GPNMB), also known as osteoactivin given its role in osteopetrosis in rats, is widely expressed in various types of cells such as macrophages, dendritic cells, osteoblasts, melanocytes, neurons and hepatocytes." (PMID 36875463, 2023).